FOXP2 (forkhead box P2)
Diseases named in the same sentence as FOXP2 in open-access papers (continued):
Sharing a sentence is not in itself a finding about the gene and the disease.
breast carcinoma (continued). "The future analysis of RNA-seq and ChIP-seq of the two factors compared in different subtype cells of breast cancer would provide a foundation to describe the detailed picture of FOXP2 and FOXA2 on regulating EMT progression and metastasis of breast cancer cells." (PMID 33718155, 2021). "Together, the results suggested that FOXP2 could inhibit EMT by activating the transcription of certain genes, such as E-cadherin and PHF2, in concert with FOXA2 in breast cancer cells." (PMID 33718155, 2021). "Moreover, miR-196b promotes cell migration and invasion by targeting FOXP2 in hepatocellular carcinoma and regulates self-renewal, differentiation, and transformation by targeting HOXC8 in breast cancer stem cells." (PMID 32258122, 2020). "Notably, circular RNA SHKBP1 was upregulated in malignant glioma targeting FOXP1 or FOXP2, while circular RNA ZNF609 and MYO9B were upregulated in renal cancer and breast cancer, respectively, targeting FOXP4." (PMID 31815635, 2019). "Another significant result of this study revealed that FOXP3 expression predicted the breast cancer cells’ response to anticancer drugs, whereas FOXP1, FOXP2 and FOXP4 did not predict." (PMID 35614183, 2022). "Furthermore, FOXP2 harbors a binding domain for the co-repressor CtBP1 (C-Terminal Binding Protein-1) which has been experimentally validated and may be involved as a tumor suppressor in oncogenic processes through interaction with the BRCA1/2 breast cancer oncofactors." (PMID 29725501, 2018).
Cognitive impairment (18 papers, 2010 to 2025). Abnormal cognition is characterized by deficits in thinking, reasoning, or remembering. "Our previous studies have reported that one of the FOXP2 polymorphisms, rs10447760 within the 5’ regulatory region, is associated with clinical outcomes and cognitive deficits in chronic schizophrenia." (PMID 35992594, 2022). "Pathogenic microdeletions involving the FOXP2-MDFIC region resulting in language or cognitive impairment have been reported." (PMID 31046704, 2019). "Microdeletions affecting the FOXP2-MDFIC intergenic region have been reported to be associated with speech or cognitive impairment." (PMID 31046704, 2019). "In the past, members of the FOXP subfamily have been implicated in various human diseases, but only FOXP1 and FOXP2 have been linked to cognitive disorders so far." (PMID 22736078, 2012). "In addition, human mutations in both FOXP1 and FOXP2 lead to severe speech and cognitive impairments and, both genes have also been linked to autism spectrum disorders." (PMID 34723967, 2021). "Forkhead box P2 (Foxp2) is another transcription factor involved in early VaD and improves cognitive impairment in rats with VaD through the upregulation of synaptic proteins through the miR-134-5p/Foxp2/Syn1 axis." (PMID 36203804, 2022). "It has been found that miR-134-5p can act on Forkhead box P2 (Foxp2) mRNA to affect its level of expression; however, silencing Foxp2 minimizes the effect of miR-134-5p on synaptic protein loss, which may prevent the development of cognitive impairment, especially in vocal learning." (PMID 35592472, 2022). "In the last 2 years, evidence has emerged that implicates FOXP1 (OMIM 605515), the closest relative of FOXP2 (64 % total protein sequence identity, 89 % in the forkhead domain), in the pathology of human cognitive disorders, which involve language impairment." (PMID 22736078, 2012). "It is important to note that FOXP2-related reading impairment would not meet the criteria for dyslexia because the syndrome includes cognitive impairment." (PMID 23308072, 2012).
glioma (18 papers, 2018 to 2025). A benign or malignant brain and spinal cord tumor that arises from glial cells (astrocytes, oligodendrocytes, ependymal cells). "Another study reported that highly expressed miR-9-5p is associated with a better prognosis in GBM and inhibits glioma cell proliferation through suppression of forkhead box P2 (FOXP2)." (PMID 40002176, 2025). "SNHG1 aggravates malignancy of glioma cells through functioning as a sponge of miR-154-5p/miR-376b-3p to up-regulate FOXP2." (PMID 32536864, 2020). "FOXP1/FOXP2 are overexpressed since the upregulated molecule circ-SHKBP1 in glioma wound sequester their hunters-miR-544a/miR-379." (PMID 32518520, 2020). "The FOXP2 immunohistochemical staining results were positively correlated with WHO glioma grade classification (r = 0.278, P < 0.01)." (PMID 30728054, 2019). "This experiment only confirms that upon editing the miR-376b-3p A to I, the effect of targeting and binding FOXP2 3 ‘UTR region did not change, further demonstrating the conservative mechanism of SNHG1-miR-376b-3p-FOXP2 in the pathogenesis of glioma." (PMID 30728054, 2019). "Silencing the expression of FOXP2 inhibits the proliferation, migration, and invasion of glioma cells and promotes apoptosis; the overexpression of FOXP2 has the opposite effect." (PMID 30728054, 2019). "Collectively, this study demonstrates that the SNHG1- microRNA-154-5p/miR-376b-3p- FOXP2- KDM5B feedback loop plays a pivotal role in regulating the malignant behavior of glioma cells." (PMID 30728054, 2019). "Immunohistochemistry also showed that the expression of FOXP2 in glioma tissues was higher than that in normal brain tissues, and the expression level increased with the tumor grade." (PMID 30728054, 2019). "He, one of co-authors, has confirmed that FOXP2 involved in angiogenesis of U87 glioma-exposed endothelial cells and angiogenesis is considered to be one of the mechanisms of tumorigenesis." (PMID 30728054, 2019). "This research displayed that FOXP2 was highly expressed in glioma tissues and cells, and increased with the pathological grade of glioma." (PMID 30728054, 2019). "The results of this study suggest a novel regulatory mechanism that miR-9-5p can inhibit glioma cells proliferation by downregulating FOXP2." (PMID 31824836, 2019). "Furthermore, elevated levels of miR-9-5p were shown to inhibit glioma proliferation by downregulating FOXP2." (PMID 36649032, 2023). "AGGF1 could promote angiogenesis in glioma-exposed endothelial cells, which was regulated by FOXP2 at the transcription level." (PMID 32183046, 2020). "The results suggest that FOXP2 acts as a tumor promoting gene in glioma tissues and cells." (PMID 30728054, 2019). "In order to further understand the effect of FOXP2 on the biological behavior of malignant glioma cells, U87 and U251 cells were transfected with FOXP2 overexpression and silence plasmids, and the malignant biological behaviors of U87 and U251 cells were detected." (PMID 30728054, 2019). "The overexpression of 3 ‘UTR wild-type FOXP2 group reversed the overexpression of miR-154-5p in inhibiting proliferation, migration, and invasion of glioma cells, and reduced the apoptosis rate of glioma cells induced by overexpression of miR-154-5p (P < 0.01)." (PMID 30728054, 2019). "miR-376c could repress the malignant behavior of glioma cells by repressing FOXP2 and circulating miR-376c was significantly down-regulated in serum from glioma patients when compared with healthy control, suggesting that miR-376c is a potential diagnostic marker and treatment target for glioma." (PMID 31133802, 2019). "Another study indicated the involvement of circ-SHKBP1 in angiogenesis of glioma-exposed endothelial cells via miR-544a/FOXP1 and miR-379/FOXP2 pathways." (PMID 32549760, 2020).
glioma (continued). "In this study, we intially identified the endogenous expression of SNHG1, miR-154-5p, miR-376b-3p, FOXP2, and KDM5B in gliomas." (PMID 30728054, 2019). "(D) FOXP2–3′-UTR-Wt reversed overexpression of miR-154-5p and miR-376b-3p induced inhibition of glioma cells proliferation." (PMID 30728054, 2019). "The detection of downstream protein KDM5B was applied to the 7 groups of glioma cells transfected with miR-154-5p overexpression, miR-376b-3p overexpression, 3 ‘UTR wild-type and 3’ UTR mutant FOXP2 overexpression plasmid." (PMID 30728054, 2019). "(E) FOXP2–3′-UTR-Wt reversed overexpression of miR-154-5p and miR-376b-3p induced augmentation of glioma cells apoptosis." (PMID 30728054, 2019). "Circ-TTBK2 regulated the miR-217/HNF1b/Derlin-1 pathway to promote the progression of glioma; and circ-SHKBP1 regulated the angiogenesis of U87 glioma-exposed endothelial cells through miR-544a/FOXP1 and miR-379/FOXP2 pathways." (PMID 31179240, 2019). "circ-SHKBP1 regulated the angiogenesis of glioma-exposed endothelial cells through the miR-544a/FOXP1 and miR-379/FOXP2 Pathways." (PMID 31214170, 2019). "Similarly, the overexpression of 3 ‘UTR wild-type FOXP2 group reversed the overexpression of miR-376b-3p in inhibiting proliferation, migration, and invasion of glioma cells, and reduced the apoptosis rate of glioma cells induced by overexpression of miR-376b-3p (P < 0.01)." (PMID 30728054, 2019). "The expression of circ-SHKBP1 is elevated in glioma-exposed endothelial cells (GECs), which functions as a ceRNA via the miR-544a/FOXP1 or miR-379/FOXP2 pathway." (PMID 30111313, 2018). "Hence, circ-SHKBP1 modulated glioma angiogenesis through targeting miR-544a/FOXP1/AGGF1 and miR-379/FOXP2/AGGF1 pathway." (PMID 32061256, 2020). "Therefore, circ-SHKBP1 promoted the movement and tube formation of glioma-exposed endothelial cells to boost angiogenesis via the circ-SHKBP1/miR-544a/FOXP1 and circ-SHKBP1/miR-379/FOXP2 axis." (PMID 32518520, 2020). "In summary, this study demonstrates that SNHG1 increases the expression of FOXP2 and KDM5B by regulating the expression of miR-154-5p and miR-376b-3p, and that KDM5B itself and its downstream PI3K/Akt pathway affect the biological behavior of glioma cells." (PMID 30728054, 2019). "In this study, we demonstrated that high expression of miR-9-5p and low expression of forkhead box P2 (FOXP2) were related with better outcome in patients with GBM, and down regulated FOXP2 expression was able to inhibit glioma cells proliferation by cell cycle arrest." (PMID 31824836, 2019). "The results suggest that overexpression of miR-154-5p or miR-376b-3p can negatively regulate the expression of FOXP2, thereby affecting the transcription of target gene KDM5B by FOXP2, changing the expression of KDM5B, and inhibiting the malignant biological behavior of glioma cells." (PMID 30728054, 2019). "FOXP2 could also promote AGGF1 expression at the transcriptional level, thus enhancing proliferation and migration of vascular endothelial cells exposed to glioma." (PMID 32183046, 2020). "The relationship between FOXP2 and glioma has not been reported yet." (PMID 30728054, 2019). "In addition, the expression of circ-SHKBP1 is elevated in glioma-exposed endothelial cells (GECs), and promotes the viability, migration and tube formation of GECs via the miR-544a/FOXP1 or miR-379/FOXP2 pathway via the AGGF1 itself or though the PI3K/AKT and ERK 1/2 pathways." (PMID 30111313, 2018).
apraxia (17 papers, 2013 to 2025). Apraxia is a neurological disorder characterized by the inability to perform tasks or movements, despite having the desire and physical ability to perform them. "As a well-known example, disruptions in the gene FOXP2 have been shown to be causal for childhood apraxia of speech within certain families, transmitted from affected parents to roughly half of the children in a monogenic autosomal-dominant manner." (PMID 41105951, 2025). "Despite the clear genetic cause, the downstream effects of how variants of FOXP2 lead to childhood apraxia of speech are still under investigation." (PMID 41105951, 2025). "Members of the KE family, in whom mutations of the FOXP2 gene cause verbal dyspraxia, exhibit abnormalities in speech-evoked neural responses and cortical gray matter thickness exclusively in the left hemisphere." (PMID 37739786, 2023). "We review the history of discoveries concerning the KE family, in whom a hereditary form of communication impairment was identified as childhood apraxia of speech and linked to dysfunction in the FOXP2 gene." (PMID 35690736, 2022). "Currently, FOXP2 is mainly known as a gene linked to childhood apraxia of speech and speech motor planning deficits." (PMID 34539327, 2021). "Mutations in FOXP2 are a monogenic cause of childhood apraxia of speech (SPCH1, OMIM #602081) and CNTNAP2 is functionally implicated in the aetiology of this condition as part of the downstream network of FOXP2 target genes." (PMID 34641913, 2021). "Heterozygous mutations of FOXP2 cause Childhood Apraxia of Speech, also referred to as Developmental Verbal Dyspraxia31." (PMID 33976169, 2021). "Heterozygous mutations of the Forkhead-box protein 2 (FOXP2) gene in humans cause childhood apraxia of speech." (PMID 30187194, 2018). "Moreover, CHD3 protein interacts with FOXP2, which is known to be implicated in language problems in Childhood Apraxia of Speech." (PMID 40881826, 2025). "Also, the p.Arg514His is equivalent to the FOXP2 p.Arg553His mutation identified in childhood apraxia of speech." (PMID 29090079, 2017). "A report of a mother and son with CAS and a submicroscopic deletion of FOXP2 also described apraxia, dysarthria and cognitive language profiles similar to those in the KE family and the mother-and-daughter studies." (PMID 24083349, 2013). "In addition, the affected family members had symptoms of verbal apraxia and lowered nonverbal cognition, suggesting complex wide-ranging effects of the FOXP2 gene." (PMID 29559943, 2018).
autism spectrum disorder (15 papers, 2010 to 2026). A spectrum of developmental disorders that includes autism, and Asperger syndrome. "Recent advances in the genetics of neurodevelopmental disorders (NDDs) have identified the transcription factor FOXP2 as one of numerous risk genes, e.g. in autism spectrum disorders (ASD) and attention-deficit/hyperactivity disorder (ADHD)." (PMID 34650032, 2021). "In humans, mutations in the transcription factor encoding gene, FOXP2, are associated with language and Autism Spectrum Disorders (ASD), the latter characterized by deficits in social interactions." (PMID 34421555, 2021). "Another correlation which remains to be functionally elucidated is between FOXP2 dysfunction and autism spectrum disorder (ASD)." (PMID 29725501, 2018).
dyslexia (15 papers, 2010 to 2024). A learning disorder characterized by an impairment in processing written words. "The authors report that the dyslexia-associated SNP rs12533005 in FOXP2 was associated with grapheme-phoneme correspondence abilities (linking letters to speech sounds) in written language in an inferior parietal area near Wernicke’s region involved in phonological processing." (PMID 34539327, 2021). "KIAA0319, FOXP2, and DCDC2-KIAA0319 SNPs correlated with dyslexia; DCDC2-DYX1C1 SNPs associated with ADHD; COMT1, MAOA, DBH SNPs correlated with different dysfunctions." (PMID 36970271, 2023). "Our literature evaluation provided a link between FOXP2 and dyslexia and SLI." (PMID 34539327, 2021). "Interestingly, markers within KIAA0319 and FOXP2 were significantly related to dyslexia when comorbid samples were included (Dys+Com-vs-Ctr_Dys), as well as when comorbids were analyzed as an independent group (Com-vs-Ctr_Dys/Com-vs-Ctr_ADHD/Com-vs-Ctr_Com)." (PMID 30379906, 2018). "Interestingly, FOXP2 and COMT have been found to be associated with dyslexia and with attentional tasks in our case-control study, although these genes are not related to reading variables in the general population." (PMID 30379906, 2018). "Intriguingly, there are suggestive linkage signals for dyslexia on chromosome 7q32, but no mutations in FOXP2 were found in dyslexic individuals from the six families that contributed to the linkage signal." (PMID 23308072, 2012). "For example, the forkhead box P2 (FOXP2) gene has a significant role in the pathogenesis of stuttering and dyslexia." (PMID 38021798, 2023). "Dyslexia candidate genes have been correlated with tasks measuring phonological abilities, such as DYX1C1 and FOXP2 with short-term memory or phonological memory, or DCDC2 and KIAA0319 with phoneme awareness itself." (PMID 30379906, 2018). "ROBO1, a candidate for dyslexia, is also highly upregulated, whereas, TLE3, a target of FOXP2, is significantly downregulated." (PMID 29922639, 2018). "We examined 4 SNPs located on genes previously associated to dyslexia (KIAA0319, DCDC2, DYX1C1 and FOXP2) and 3 SNPs within genes related to ADHD (COMT, MAOA and DBH) in a cohort of Spanish children (N = 2078) that met the criteria of having one, both or none of these disorders (dyslexia and ADHD)." (PMID 30379906, 2018). "These attentional tasks are not usually analyzed with dyslexia candidate genes, therefore, one intriguing result obtained from our cohort is the relationship of this type of task with KIAA0319, FOXP2 and DYX1C1 SNPs." (PMID 30379906, 2018).
Intellectual disability (14 papers, 2015 to 2025). "In the brain, the transcription factor, FOXP1, heterodimerizes with its paralog, forkhead box P2 (FOXP2), to form a transcription factor; rare mutations in FOXP2 have been reported in multiple cases of intellectual disability and language impairment." (PMID 38028628, 2023). "Variants in FOXP1 and FOXP2 can lead to mental retardation with language impairment (MIM#613670) and Speech-language disorder-1 (MIM#602081), respectively." (PMID 27435318, 2016). "For most of the genetic conditions, the presence of intellectual disability was confirmed or parent‐reported, except for individuals with the BRPF1 or FOXP2 variants." (PMID 39846212, 2025). "Notably, in most previous reports on ASD and intellectual disability, PAX6, TBR1 and FOXP2 were either deficiently expressed or had lost functions." (PMID 31699123, 2019). "FOXP2 is known to regulate CNTNAP2 expression by binding to a regulatory sequence in its first intron, and CNTNAP2 dysfunctions have been implicated in specific language impairments, intellectual disabilities, and ASDs." (PMID 29345619, 2018).